ERBB2 (erb-b2 receptor tyrosine kinase 2)
Diseases named in the same sentence as ERBB2 in open-access papers (continued):
Sharing a sentence is not in itself a finding about the gene and the disease.
tumor (continued). "Therefore, ERBB2/3 and EGFR are ideal tumor-associated antigens, which are suitable for binding with T and B cell activators such as CD3 and CD40 agonists to construct bispecifics, and kill tumor cells by bridging immune cells to tumor." (PMID 38713378, 2024). "To this end, we followed homozygous female Erbb2/Cre/Pfkfb3fl/fl mice for the development of palpable mammary masses and, when tumor development was observed and burden reached ~100 mg, randomized mice to intraperitoneal administration of vehicle ± TAM for 5 days." (PMID 39001392, 2024). "Furthermore, mouse CAR T-cells were able to provide an acceptable anti-tumor effect in vivo for different tumor antigens (e.g., ERBB2, CEA, TAG-72, FBP)." (PMID 38672680, 2024). "A repeat biopsy following the development of lurbinectedin resistance showed a new actionable ERBB2 alteration without significant change in the tumor mutation burden (six mutations/Mb)." (PMID 38920737, 2024). "As such, these drugs may offer hope for other tumour types that show ERBB2 gene amplification, such as 2–5% of non-small cell lung cancer patients." (PMID 38787171, 2024). "However, the ERBB2-targeting antibodies trastuzumab and pertuzumab block the formation of signaling-competent ERBB3/ERBB2 heterodimers, and this mechanism has been shown to be critical for the anti-tumor effect." (PMID 38806620, 2024). "The overexpression of ERBB2 or ERBB3 partially offset the anti-tumor effects of SD." (PMID 39549017, 2024). "To validate our findings that the engineered destabilized 3’UTR of ERBB2 degrades ERBB2 in vivo and reduces ERBB2-driven tumor growth and volume in a mouse tumor-bearing model, we implanted 25 female NSG mice with 5 million NCI-H1975 cells on the flank and after 35 days, huge tumors engrafted." (PMID 37359373, 2023). "Our results are not in agreement with those of a previous study, but the reason could be due to the different ERBB2+ tumor type studied." (PMID 37367744, 2023). "Similarly, age, educational attainment, menopause status, number of positive nodes, ERBB2 and hormone receptor status, tumor subtype, smoking status, and the LIS were significantly associated with mortality." (PMID 37140922, 2023). "Tumor grade and ERBB2 copy number could account for some of these within-subtype disparities, but further studies are warranted." (PMID 36995711, 2023). "To more precisely study the potential role of ERBB2 in signalling through AP-1 in OAC, we compared the accessible chromatin landscape of three ERBB2 amplified OAC tumours to Barrett's oesophageal samples (the precursor to OAC) and nine OAC samples lacking such amplifications." (PMID 36694726, 2023). "In this context, we and others demonstrated that, indeed, Ca2+/CaM binds to and regulates ErbB2 and its downstream signaling pathways, as CaM inhibition or deletion of the CaM binding sites inhibit ErbB2-mediated signaling, decreasing tumor cells proliferation." (PMID 36979639, 2023). "It was confusing that EGFR and ERBB2 had low expression in tumor tissue compared to normal tissue whether in GEO or TCGA data, perhaps due to the disadvantage of bulk sequencing." (PMID 38348352, 2023). "Pancancer analysis revealed differential expression of ERBB2 across various tumor tissues." (PMID 37324014, 2023). "Beyond the well-known ERBB2/HER2 or MET amplification-associated dependencies, there are other gene dependencies identified in the analysis that show promising results in selected tumor types." (PMID 36980521, 2023). "Notably, tumor regression resulted from adoptive cell therapy (ACT) using endogenous tumor-infiltrating CD4+ T lymphocytes recognizing a mutant ERBB2 protein in a patient with metastatic epithelial carcinoma." (PMID 37892995, 2023).
tumor (continued). "Finally, we compared expression between groups defined by clinical factors (tumor size and type, node status, molecular subtype, ERBB2, and progesterone receptor." (PMID 37491786, 2023). "Additionally, we studied the expression of key proteins involved in the EMT process, including E-cadherin and vimentin, and of proteins related to the tumor phenotype, such as ER, PR, ERBB2, Ki-67, cytokeratin (CK) 8/18, CK5/6, CK14, and CD44." (PMID 36899736, 2023). "(ii) Receptor tyrosine kinases (RTK): The activation of RTKs, such as EGFR, ERBB2, KIT, and PDGFR, by mutation or translocation directly leads to tumor growth and is a clear therapeutic target; these mutations were detected in 216 of 1003 cases or around 20% of the cases." (PMID 36251535, 2023). "Our finding underlines that therapy targeting PGAP3‐ERBB2 amplicon may provide additional benefit over targeting ERBB2 alone for patients with tumours carrying 17q12 amplification." (PMID 37386793, 2023). "Additionally, it was reported that sema3E induces invasiveness and metastatic spreading of tumor cells through the transactivation of ErbB2 by a post-translationally modified sema3E that was truncated by furin-like pro-protein convertases (P61-sema3E)." (PMID 37627074, 2023). "MUC4 may act as an intramembrane ligand for the receptor tyrosine kinase ErbB2 and perform an anti-apoptotic function to promote tumor progression." (PMID 37384668, 2023). "Concerning copy number aberrations (CNAs), the top amplified genes in the samples from the primary tumor were ERBB2 (6/19, 32%), AURKA, PPM1D (4/19, 21%), and FGFR1 (3/19, 16%), while in the metastatic samples ERBB2 (7/17, 41%), CDK12, FGFR1 (4/17, 24%), and AURKA, MDM4, MYC (3/17, 18%)." (PMID 36717329, 2023). "Furthermore, in other tumor types, the frequency of ERBB2 overexpression has differed in the literature and has often been higher than the gene amplification rate, suggesting that ERBB2 overexpression is due to gene deregulation rather than amplification." (PMID 37173881, 2023). "ERBB2 is an oncogene that drives tumor progression via activation of PI3K/Akt pathway." (PMID 37325934, 2023). "Herein we report a case of a patient with metastatic HCC and large disease burden who was serendipitously found to have a very high ERBB2 copy number amplification by circulating tumor DNA (ctDNA) liquid biopsy, prompting us to perform confirmational testing and act on this actionable marker." (PMID 40028484, 2023). "Furthermore, in a model in which BlgCre activated an Erbb2/HER2 orthologue, tumour histotype varied from AC(NST) in virgin animals to ASQC in parous animals." (PMID 37686600, 2023). "Furthermore, the methylation of the ERBB2 promoter was significantly lower in tumor tissues than in normal tissues." (PMID 37324014, 2023). "Based on these findings, we hypothesized that the 3’UTR of oncogenes such as ERBB2 will be enriched with poly U mRNA-stabilizing elements, which stabilize their transcripts and drive tumor aggressiveness." (PMID 37359373, 2023). "The hypoxia-activated EGFR/HER2 inhibitor tarloxotinib, may be another mechanism of more specifically targeting EGFR or ERBB2 fusions in only tumor cells." (PMID 37168365, 2023). "The oncogene of HER2, ERBB2, is located on chromosome 17q12.Amplification of HER2 is the primary cause of overexpression of its receptor and this amplification plays a plays a key role in tumor formation and development." (PMID 38352694, 2023). "Furthermore, ErbB2, once overexpressed in a tumour, exhibited homodimerization and resulted in tumour growth and often failure in treatment." (PMID 38203605, 2023).
tumor (continued). "Also, it is known that the genetic alteration related to tumor development include the mutations in PIK3CA, AKT1, ERBB2, and RAS/RAF pathway." (PMID 37264748, 2023). "Here, we generated NK cells carrying a first- or second-generation universal CAR (UniCAR) and redirected them to tumor cells with so-called target modules (TMs) which harbor an ErbB2 (HER2)-specific antibody domain for target cell binding and the E5B9 peptide recognized by the UniCAR." (PMID 36688995, 2023). "To determine whether CAR-Ms specifically recognize HER2-positive tumor cells, we constructed a lentiviral vector that expressed a truncated human ERBB2 gene." (PMID 36978075, 2023). "ERBB2 triggers several signaling pathways involved in tumor growth." (PMID 36900367, 2023). "Moreover, our further analysis showed that the higher expression level of ERBB2, the higher differentiation stage of tumor cells, indicating a possible connection between ERBB2 expression and tumor development in TNBC." (PMID 36998014, 2023). "However, our results show that both EGFR and ERBB2 play a significant role in PDAC and their loss leads to slowed tumor growth." (PMID 37341059, 2023). "In addition, one additional tumor with equivocal HER2 IHC score of 2 + both pre- and post-NET showed ERBB2 gene amplification post-NET." (PMID 37066270, 2023). "In contrast, BARD1 low expression was significantly associated with low tumor grade and non-papillary tumor shape in ERBB2-high patients." (PMID 37474724, 2023). "The clinical application of the ErbB2 specific CAR T cells with the herceptin derived 4D5 scFv binding domain, produced fatal side effects, most likely due to the off-tumor on-target activation of the CAR T cells against the healthy tissues with physiological ErbB2 levels." (PMID 36672182, 2023). "Multivariable analysis showed that CH-PD presence was independently associated with worse OS (HR, 1.52 [95% CI, 1.06-2.20]; P = .02) after accounting for age, prior therapies (radiotherapy and/or chemotherapy) and tumor characteristics (ERBB2 status and MSI-H)." (PMID 36729457, 2023). "Interestingly, the epidermal growth factor receptor (EGFR) family can also be activated, and bile acids induce the overexpression of ERBB2 (HER2) in the tumor tissue contacted, leading to a significantly worse prognosis." (PMID 35406597, 2022). "Moreover, ERBB2 E401G-transduced cells showed an increased invasive capacity in vitro and an increased tumor growth capacity in vivo." (PMID 34997908, 2022). "Draws 4 and 6 showed the gain of a new ERBB2 mutation (G776V) in the tyrosine kinase intracellular domain which was not identified in the tumor pathology at the start of therapy." (PMID 35181666, 2022). "In BC, FAK activation has been shown to be required for ErbB2-mediated oncogenic transformation, invasion and tumor progression in vivo, while SRC-mediated FAK tyrosine phosphorylation at multiple residues has been demonstrated to play an important role in full FAK activation." (PMID 36581908, 2022). "Responses to treatment correlated with higher ErbB2 mRNA expression in tumor tissue." (PMID 35384591, 2022). "Notably, one TNBC patient presented with an ERBB2 CNV, indicating tumour heterogeneity and the potential need to reassess HER2 status by ctDNA during the clinical management of TNBC." (PMID 35562750, 2022). "In contrast, overexpression of ERBB2 in KYSE150 cells enhanced the tumor growth." (PMID 35524932, 2022). "Furthermore, liquid biopsy-based circulating tumor DNA profiling detected an ERBB2 copy number amplification." (PMID 35433426, 2022).
tumor (continued). "Furthermore, LAR tumours and cell line models display high dependencies on AR, FOXA1, ERBB2, and AKT protein and phospho-protein signalling, as well as frequent PIK3CA and ERBB2 mutations." (PMID 36077812, 2022). "ERBB2 amplification occurs in ~ 2% of PDAC tumours and may outline a suitable sub-population for targeted treatment with anti-ERBB2 therapies." (PMID 35392854, 2022). "The dynamic variations of ERBB2 during tumor progression and treatment are also unclear; this includes the manner in which chemotherapy could influence ERBB2 expression." (PMID 36291943, 2022). "HER2 (synonym: ErbB2) is a cell-surface receptor with a transmembrane tyrosine kinase domain that plays a crucial role in tumor biology through the downstream activation of the PI3K/Akt pathway (call polarity, cell adhesion, cell cycle) and the MAPK pathway (mitosis) in multiple cancers." (PMID 36428670, 2022). "ERBB2 plays an important role in normal cell and tumor development." (PMID 35915735, 2022). "Currently developed nanoparticles targeting ERBB2 can enhance ICD effects at tumor sites." (PMID 36425071, 2022). "The assay integrates clinical information (i.e., tumour size and nodal status) with biological information tracking immune response, luminal differentiation, tumour cell proliferation and expression of the HER2 17q12-21 chromosomal amplicon, including the ERBB2 gene." (PMID 36374768, 2022). "Results: 176 patients had NGS revealing an ERBB2 CNG (112 by tumor tissue and 91 by ctDNA)." (PMID 35126865, 2022). "In addition, the inferred tumor ERBB2 ploidy by QASeq was consistent with the available tumor ploidy from FISH." (PMID 35379811, 2022). "Interestingly, ERBB2 copy number gains detectable in blood corresponded well with findings from the tumour tissue in patients with HER2 positivity." (PMID 35158855, 2022). "Moreover, PPARGC1A levels are already elevated in samples from patient OAC tumours containing high ERBB2 levels compared to the precursor Barrett’s oesophagus." (PMID 36153371, 2022). "Additionally, the relationship between ERBB2 gene expression and the immune micro-environment of various tumor types is elusive." (PMID 36172165, 2022). "Studies indicate that ERBB2 oncogenic activity from tumor ERBB2 overexpression may depend on the presence of ERBB3." (PMID 36291943, 2022). "It inferred that antirheumatic medicine could stop the formation of ERBB2 homologous dimers, prevent cell proliferation, and kill tumor cells." (PMID 35069767, 2022). "Interestingly, regardless of the presence or absence of mutations in these genes in ESCC, their products (ERBB2 and MET) are often overexpressed in tumor tissues, indicating their vital carcinogenic role in ESCC." (PMID 35739509, 2022). "In accordance with the imaging and survival results, we found that ErbB2CAR IP treatments at both low and high doses resulted in a reduction in ErbB2-positive tumor cells in the ovary, and that the outcome was related with low numbers of ErbB2-expressing cells." (PMID 36140319, 2022). "In addition to evaluation of tumor tissue biopsy specimens, ERBB2 amplification can be identified by non-invasive methods, including assessment of ERBB2 overexpression in circulating tumor cells or measurement of ERBB2 copy numbers via NGS of cell-free DNA." (PMID 36291943, 2022). "QASeq detected ERBB2 amplification in plasma cfDNA 5 months earlier than FISH from tumor tissue." (PMID 35379811, 2022). "Furthermore, CB2 receptor-mediated inhibition of Akt has been reported in ErbB2-positive breast cancer progression in mouse mammary tumour virus (MMTV)/neu transgenic mice as a syngeneic tumour model." (PMID 35277658, 2022). "ELAVL1 could promote the proliferation of tumor cells by directly binding ER or regulating epidermal growth factor receptor-2 (ERBB2), cyclooxygenase-2 (COX-2) and VEGF-A through a series of signal transduction pathways." (PMID 36261786, 2022).
tumor (continued). "Similarly, the findings of this study revealed that GC with a glycolytic phenotype had higher inflammation and a lower ERBB2 expression level, which was consistent with the role of glycolysis in tumour aggressiveness and the inflammatory milieu in GC." (PMID 35990657, 2022). "Ptk6 (Brk) expression was shown to enhance the formation of murine ErbB2-induced tumours in cleared fat pads with a shorter latency period than ErbB2-only tumours, and both constitutively active and wild-type Brk promoted xenograft growth of MDA-MB-231 basal breast carcinoma cells." (PMID 35327957, 2022). "Moreover, Notch 3 is an oncogenic factor for ER+ and HER2+ human patients, but a tumor suppressor for TNBC cell lines and ERBB2 basal tumor cells." (PMID 35406423, 2022). "For the Type 2 T-helper cells, the Her2 + tumor and the luminal subtypes were identified, and the most relevant process implicated were the ERBB2 signaling pathway and the Fibroblast Growth Factor Receptor (FGFR) signaling pathway located in chromosomes 8q, 11q, and 17q." (PMID 36119512, 2022). "BC is categorized the following established criteria: tumor morphology, grade, stage, and expression of key genes, such as estrogen receptor-α (ER), progesterone receptor (PR), and human epidermal growth factor receptor-2 (HER2 or ERBB2), to determine adequate treatment options." (PMID 36233192, 2022). "Furthermore, we found through the GEPIA database that increased ERBB2 expression correlates with tumor stage and predicted a poor prognosis in NPC patients." (PMID 37304410, 2022). "Our results revealed the critical roles of ERBB2 gene demethylation and tumor immune cell infiltration, indicating that the survival of cancer patients could be modulated by improving immune cell infiltration and ERBB2 demethylation in various cancers." (PMID 36172165, 2022). "Thus, we analyzed the data derived from online repositories, including TCGA, KEGG, GO, GeneMANIA, and STRING, to explore the relationship between ERBB2 expression and prognosis, tumor phenotypes of interest, and immune infiltrates in PTC." (PMID 36437939, 2022). "ERBB2 plays a role in tumor cells by binding to other epidermal growth factor receptors (EGFRs) and then generating a dimer form that activates signaling pathways related to tumor proliferation." (PMID 35069767, 2022). "The same group also showed that tumor growth was reduced by single targeting of ERBB2 in cetuximab-resistant, quadruple (i.e., KRAS, NRAS, BRAF, and PIK3CA) wt CRC patient derived xenografts with ERBB2 mutations." (PMID 35582524, 2022). "Furthermore, concomitantly treating CRPC cells with the abiraterone and ErbB2 inhibitor, lapatinib, blocked AR reactivation and suppressed tumor progression." (PMID 35645241, 2022). "CCL5, another cytokine produced by adipocytes, has also been shown to enhance TAM recruitment into residual tumors in a conditional model of ErbB2 overexpression in mice, leading to increased collagen deposition within the tumor site and eventual recurrence of the tumor." (PMID 35435599, 2022). "The result revealed that the tumor immune infiltration was different in AR and ERBB2 expression." (PMID 35069767, 2022). "Our study demonstrated ERBB2 CNG found on NGS testing across over 10 different tumor types." (PMID 35126865, 2022). "The immune cell infiltration could deteriorate the tumor micro-environment and decrease the survival of patients, indirectly suggesting the essential role of the ERBB2 gene demethylation in mediating immune response." (PMID 36172165, 2022). "Since MOC is a highly heterogenous tumor with mixed areas of mucinous cystadenoma and borderline lesions, it is likely that ERBB2 therapies may be effective only on some tumor cells within MOC leaving the remaining tumor cells intact." (PMID 35359749, 2022).